REPS1 (RALBP1 associated Eps domain containing 1)
Description:
May coordinate the cellular actions of activated EGF receptors and Ral-GTPases.
Synonyms: NBIA7
Tractability: Antibody: its Gene Ontology location is reachable by antibodies, with high confidence; the Human Protein Atlas places it where antibodies can reach. PROTAC: ubiquitination databases record sites on it; its protein half-life has been measured.
Gene: Protein-coding gene on chromosome 6 (138,903,493 to 138,988,354, reverse strand). Ensembl gene ENSG00000135597.
Subcellular location: Membrane, clathrin-coated pit
Subcellular location (Human Protein Atlas): Plasma membrane; Cytosol; Vesicles
Pathways (Reactome):
Vesicle-mediated transport: Cargo recognition for clathrin-mediated endocytosis; Clathrin-mediated endocytosis
Gene Ontology:
Molecular function: protein binding; SH3 domain binding; protein-macromolecule adaptor activity; calcium ion binding
Cellular component: clathrin-coated pit; plasma membrane; cytosol
Genetic constraint (gnomAD): Loss-of-function variants: 25 observed, 59.62 expected, observed/expected ratio (o/e) 0.42, 90% interval 0.31 to 0.59. The upper end of that interval is the gene's LOEUF score, 0.59, which puts it in group 2 of 6, group 1 being the genes least tolerant of losing a copy. Missense variants: 587 observed, 703.55 expected, observed/expected ratio (o/e) 0.83, 90% interval 0.78 to 0.89. Synonymous variants: 247 observed, 256.07 expected, observed/expected ratio (o/e) 0.96, 90% interval 0.87 to 1.07.
Homologues: Orthologues: chimpanzee REPS1 (99% identical), macaque REPS1 (99% identical), dog REPS1 (98% identical), pig REPS1 (97% identical), mouse Reps1 (95% identical), rat Reps1 (95% identical), guinea pig REPS1 (92% identical), rabbit REPS1 (90% identical), zebrafish reps1 (72% identical), tropical clawed frog reps1 (54% identical), Drosophila melanogaster Eps-15 (15% identical), Caenorhabditis elegans ehs-1 (12% identical), and 2 more. Paralogues in human: REPS2 (34% identical), EPS15L1 (19% identical), EPS15 (17% identical), ITSN2 (16% identical), ITSN1 (15% identical), EHD3 (8% identical), EHD1 (8% identical), EHD4 (8% identical), EHD2 (7% identical), SRL (5% identical).
Diseases named in the same sentence as REPS1 in open-access papers:
REPS1 is named in the same sentence as 15 diseases in open-access papers, as found by Europe PMC text mining. Sharing a sentence is not in itself a finding about the gene and the disease. The quoted sentences say what the papers report.
chronic kidney disease (1 paper, 2025). Impairment of the renal function secondary to chronic kidney damage persisting for three or more months. "Intriguingly, two lead variants within REPS1 introns (rs7870658 and rs2750415) are associated with cardiometabolic diseases in T2D, such as coronary artery disease and chronic kidney disease." (PMID 40482643, 2025).
Insulin resistance (1 paper, 2025). Increased resistance towards insulin, that is, diminished effectiveness of insulin in reducing blood glucose levels. "REPS1 phosphorylation correlates with insulin sensitivity and is impaired in insulin resistance, highlighting its role in metabolic regulation." (PMID 40482643, 2025). "The skeletal muscle-tissue-specific insulin response and impairment in insulin-resistant mice and humans emphasize the clinical relevance of REPS1 as a potential therapeutic target for diseases characterized with insulin resistance, such as T2D." (PMID 40482643, 2025). "This alignment leads us to posit that REPS1 may serve as a pivotal signaling node in humans, holding substantial clinical relevance for metabolic diseases characterized by insulin resistance." (PMID 40482643, 2025). "Moreover, insulin action on REPS1 S709 phosphorylation was impaired in several in vivo models of insulin resistance and strongly correlated with insulin sensitivity." (PMID 40482643, 2025). "Together, these results highlight the role of REPS1 as a key signaling protein impaired in insulin resistance and suggest that enhancing REPS1 phosphorylation could be a potential therapeutic strategy to improve insulin sensitivity and restore glucose uptake in metabolic disorders such as T2D." (PMID 40482643, 2025).
microcephaly (1 paper, 2024). A congenital or acquired developmental disorder in which the circumference of the head is smaller than normal for the person's age and sex. "Mnb/DYRK1A and Reps/REPS1/2 physically interact in both Drosophila and human cells, suggesting conservation of this interaction and a potential novel regulatory axis for DYRK1A-related diseases such as microcephaly." (PMID 39271109, 2024).
tumor (5 papers, 2018 to 2024). "MC-38 tumor-bearing mice, which were injected with the mutated peptide vaccine (Adpgk, Reps1, and Dpagt1), showed the suppression of tumor growth." (PMID 30662919, 2018). "The impairment of CD8 T cell response did not depend on the source of antigen, as it was observed with antigens of viral (HPV-E7 and VSV-GP) origin as well as tumor specific neoantigens (adpgk, reps-1, rpl-18), which exhibit a wide range of immunogenicity." (PMID 38893156, 2024). "With regards to tumor-dLNs, KV vaccination significantly increased Adpgk-, Reps1- and Rpl18-specific CD8+ T cells compared to controls." (PMID 34885215, 2021). "The functional TCR avidity of the different antigen specificities (Adpgk, Reps1, Rpl18) was assessed in splenocytes from MC-38 tumor-bearing mice." (PMID 34885215, 2021). "Similar to as in the blood, the frequency and number of tumor-infiltrating antigen-specific CD8+ T cells were further increased when the sum of Adpgk-, Reps1- and Rpl18-specific CD8+ T cells was considered." (PMID 34885215, 2021). "Nevertheless, a significantly higher percentage of Reps1 (MC38 neo-antigen)-reactive CD8+ T cells was present within MC38/Nb1 (12.6 ± 3.6%) compared to MC38/BCII10 (4.6 ± 3.3%) tumors, suggestive of an enhanced anti-tumor CD8+ T cell response." (PMID 33266104, 2020). "In addition, polyfunctional Adpgk but not Reps1 nor Rpl18-specific tumor-infiltrating CD8+ T cells were observed in the KV group." (PMID 34885215, 2021).
genetic diseases (1 paper, 2022). "Mutations in REPS1 can reduce palmitoylation as well as altered acylation in genetic diseases." (PMID 35813961, 2022).
metabolic disorders (1 paper, 2025). "Moreover, phosphorylation of REPS1 strongly correlated with insulin sensitivity and was specifically impaired in skeletal muscle under insulin-resistant conditions, emphasizing its potential relevance in metabolic diseases such as T2D." (PMID 40482643, 2025).
myopathy (1 paper, 2022). A disease of the muscle in which the muscle fibers do not function properly. "Forty-six candidate genes are prioritized by multiple approaches (42 for LST and 6 for MVPA; 2 overlap) and point to endocytosis (CNIH2, RAB1B, KLC2, PACS1, REPS1, DNM3, EXOC4), locomotion (CADM2, KLC2) and myopathy (MLF2, HERC1, KLC2, SIL1) as relevant pathways." (PMID 36071172, 2022).
REPS1 also shares sentences with these, for which no sentence is quoted: Alzheimer disease (1 paper); colon adenocarcinoma (1); colorectal carcinoma (1); coronary artery disease (1); hematologic malignancies (1); melanoma (1); tuberculosis (1); vascular dementia (1).